ZER1 (zyg-11 related cell cycle regulator)
Description:
Serves as substrate adapter subunit in the E3 ubiquitin ligase complex ZYG11B-CUL2-Elongin BC. Acts to target substrates bearing N-terminal degrons for proteasomal degradation with the first four residues of substrates being the key recognition elements. Involved in the clearance of proteolytic fragments generated by caspase cleavage during apoptosis since N-terminal glycine degrons are strongly enriched at caspase cleavage sites. Also important in the quality control of protein N-myristoylation in which N-terminal glycine degrons are conditionally exposed after a failure of N-myristoylation.
Synonyms: C9orf60; ZYG; ZYG11BL; Hzyg
Tractability: PROTAC: ubiquitination databases record sites on it; its protein half-life has been measured.
Gene: Protein-coding gene on chromosome 9 (128,729,785 to 128,772,414, reverse strand). Ensembl gene ENSG00000160445.
Subcellular location (Human Protein Atlas): Cytosol
Gene Ontology:
Molecular function: protein binding
Biological process: positive regulation of proteasomal ubiquitin-dependent protein catabolic process; protein quality control for misfolded or incompletely synthesized proteins; proteasome-mediated ubiquitin-dependent protein catabolic process
Cellular component: Cul2-RING ubiquitin ligase complex
Genetic constraint (gnomAD): Loss-of-function variants: 11 observed, 75.61 expected, observed/expected ratio (o/e) 0.15, 90% interval 0.091 to 0.24. The upper end of that interval is the gene's LOEUF score, 0.24, which puts it in group 1 of 6, group 1 being the genes least tolerant of losing a copy. Missense variants: 581 observed, 990.27 expected, observed/expected ratio (o/e) 0.59, 90% interval 0.55 to 0.63. Synonymous variants: 389 observed, 403.35 expected, observed/expected ratio (o/e) 0.96, 90% interval 0.89 to 1.05.
Homologues: Orthologues: chimpanzee ZER1 (99% identical), macaque ZER1 (99% identical), dog ZER1 (98% identical), guinea pig ZER1 (97% identical), mouse Zer1 (96% identical), rat Zer1 (96% identical), rabbit ZER1 (95% identical), pig ZER1 (93% identical), tropical clawed frog zer1 (84% identical), zebrafish zer1 (67% identical), Drosophila melanogaster CG12084 (36% identical), Caenorhabditis elegans zer-1 (34% identical). Paralogues in human: ZYG11B (27% identical), ZYG11A (24% identical).
Diseases named in the same sentence as ZER1 in open-access papers:
ZER1 is named in the same sentence as 5 diseases in open-access papers, as found by Europe PMC text mining. Sharing a sentence is not in itself a finding about the gene and the disease. The quoted sentences say what the papers report.
cervical cancer (2 papers, 2022 to 2023). A primary or metastatic malignant neoplasm involving the cervix. "In our immunoprecipitation experiments, the ZER1 protein was readily detectable in the cervical cancer cell lines." (PMID 36346242, 2022). "Cancer dependency data suggest that ZER1 is essential in many HPV-positive cervical cancer cell lines, even those transformed by HPV genotypes other than HPV16." (PMID 36346242, 2022). "ZER1 interacted with HPV16 E7 in all cervical cancer cell lines, demonstrating that ZER1 is expressed and can bind to HPV16 E7 in each cell line." (PMID 36346242, 2022). "Depleting ZER1 also reduced the anchorage-independent growth of HPV-positive cervical cancer cells." (PMID 36346242, 2022). "ZER1 contributes to the anchorage-independent growth of HPV-positive cervical cancer cell lines." (PMID 36346242, 2022). "Depleting ZER1 impaired the growth of primary keratinocytes expressing HPV16 E7 or HPV18 E7 and of HPV16-and HPV18-positive cervical cancer cell lines." (PMID 36346242, 2022). "However, we confirmed that ZER1 is expressed in HPV-positive and HPV-negative cervical cancer cell lines by using HPV16 E7 as bait in coimmunoprecipitation experiments." (PMID 36346242, 2022).
uterine cancer (2 papers, 2022 to 2023). Primary or metastatic malignant neoplasm involving the uterine corpus and/or the cervix. "We graphed the data from cervical, head and neck, and endometrial/uterine cancer cell lines, finding that the ZER1 Chronos scores ranged from −0.5 to −1 for most of the HPV-positive, but not the HPV-negative, cell lines." (PMID 36346242, 2022).
cancer (1 paper, 2022). A tumor composed of atypical neoplastic, often pleomorphic cells that invade other tissues. "Nearly all the cell lines in which ZER1 is predicted to be an essential gene were from cancers caused by HPV." (PMID 36346242, 2022). "Cancer dependency data emphasized that ZER1 is an essential gene in HPV-positive cancer cells transformed with several high-risk HPV genotypes, but not in most other cancer cell lines, highlighting that there are essential genes specific to cancers caused by HPV." (PMID 36346242, 2022). "We therefore continued to investigate the importance of ZER1 in keratinocyte growth and cancer cell growth." (PMID 36346242, 2022). "The cellular protein ZER1 interacts with the E7 protein from HPV16, the genotype most frequently associated with human cancers." (PMID 36346242, 2022). "Our work emphasizes that ZER1 is an important contributor to the carcinogenic activity of high-risk HPV E7 and supports that ZER1 is essential for the growth of HPV-positive cancers." (PMID 36346242, 2022). "Next, we wanted to determine whether ZER1 was required for the anchorage-independent growth of HPV-positive cancer cell lines." (PMID 36346242, 2022). "Inhibiting ZER1 and/or the HPV16 E7-ZER1 interaction could limit the growth of cancers caused by high-risk HPV." (PMID 36346242, 2022). "Cancer gene dependency data indicated that ZER1 scored as an essential gene in nearly every HPV-positive cell line but in almost no cell lines from other cancer types." (PMID 36346242, 2022). "Given that ZER1 is essential in HPV-transformed cells regardless of HPV genotype, future studies will investigate the role of ZER1 in cancer cells caused by other high-risk HPV." (PMID 36346242, 2022). "Cancer dependency data show that ZER1 is an essential gene in most HPV-positive, but not HPV-negative, cancer cell lines." (PMID 36346242, 2022).
infection (1 paper, 2021). The state of being infected such as from the introduction of a foreign agent such as serum, vaccine, antigenic substance or organism. "If ORF10 depended on CRL2ZYG11B and/or CRL2ZER1 in order to promote infection, then ZYG11B/ZER1 KO cells would be expected to be resistant to SARS-CoV-2 infection." (PMID 33827988, 2021).
ZER1 also shares sentences with these, for which no sentence is quoted: pancreatic cancer (1 paper).